TNF (tumor necrosis factor)
Diseases named in the same sentence as TNF in open-access papers (continued):
Sharing a sentence is not in itself a finding about the gene and the disease.
atherosclerosis (continued). "In addition, the inflammatory factors, such as IL-6, TNF-α, significantly contribute to the development, progression and destabilization of atherosclerotic plaques; production of fibrinogen might be enhanced by inflammatory process associated with atherosclerosis." (PMID 26283889, 2015). "In addition to inducing foam cell formation, ox-LDL can activate macrophages to produce proinflammatory cytokines, such as TNF-α, IL-6, and IL-1β, to promote atherosclerosis." (PMID 26045945, 2015). "The present study suggests that at elevated levels, leptin may favor atherosclerosis by promoting the synthesis of TNF-α and insulin." (PMID 25762868, 2015). "This highlights that strategies aimed to modulate inflammatory actions elicited by TNFα could be promising therapeutic options to treat atherosclerosis." (PMID 26578976, 2015). "PDTC also remarkably reduced atherosclerosis and the levels of IL-1β, TNF-α and MCP-1 in plasma." (PMID 25860573, 2015). "Particularly, TNF-α is reportedly involved in the development of early atherosclerosis by up-regulating vessel wall chemokine and expression of adhesion molecules such as intercellular adhesion molecule (ICAM)-1 and vascular cell adhesion molecule (VCAM)-1 in the aorta." (PMID 26580653, 2015). "The results of the present study suggested that TNF-α may participate in the process of atherosclerosis by affecting EPC function; therefore, inhibiting these functions may be a promising therapeutic strategy for the treatment of atherosclerosis." (PMID 26095681, 2015). "Such co-expression may produce an acute induction of CX3CL1 by a wide range of proinflammatory factors, including TNF-α, LPS and hyperlipidemia, and may lead to vascular injury and atherosclerosis." (PMID 25959742, 2015). "TNF-α causes diminished VSMC cellularity via apoptosis in atherosclerosis, but this effect has not been demonstrated in IA." (PMID 25922566, 2015). "It should also be noted that cancer cells are well known to secrete pro-inflammatory cytokines such as TNF-α, IL-6, and IL-1β; all of which act to promote a local, pro-neoplastic environment (which may also influence atherosclerosis)." (PMID 26000958, 2015). "In addition, pro-inflammatory cytokines, including TNF-α and IL-6, which are involved in RA pathogenesis, play a critical role in atherosclerosis in patients with RA." (PMID 25889426, 2015). "Last but not least, TNF antagonists improve biomarkers of inflammation such as C-reactive protein, which are independent risk factors of atherosclerosis." (PMID 26633680, 2015). "The biological effects of microRNAs (miRNAs) and TNF-α in atherosclerosis have been widely studied." (PMID 26459935, 2015). "TNF-α is a vital cytokine involved in the progress of atherosclerosis." (PMID 26539229, 2015). "In addition, IPP and VPP further inhibited inflammatory signaling by TNFα, a major pro-inflammatory cytokine involved in the pathology of atherosclerosis and other inflammatory diseases." (PMID 25714093, 2015). "Inflammatory cytokines such as Tumor necrosis factor-α (TNF-α), IL-1β and IL- 6 were found to play a central role in the vicious circle of inflammation, endothelial dysfunction and atherosclerosis in patients with diabetic micro and macrovascular complications." (PMID 24822086, 2014). "Therefore, our study was the first to demonstrate the presence of a significant correlation between TNF-α, and the progression of atherosclerosis, in a sample of OSA patients." (PMID 24481114, 2014). "In our study, Homer1, like TNF-α and IL-1β, could be a potential and important participant in diagnosing early atherosclerosis, consequently, CAD." (PMID 25551602, 2014). "In agreement with atherosclerotic pathology, ox-LDL and TNF-α, two key risk factors engaged in the pathological development of atherosclerosis, were increased only in HCD-BAD rats, but not in NC-BAD rats or HCD-sham rats." (PMID 24465540, 2014).
atherosclerosis (continued). "A lot of studies have demonstrated that MCP-1, IL-1 and TNF-α levels increased in atherosclerosis." (PMID 25598757, 2014). "Although much work needs to be done to further establish the detailed mechanisms by which myocardin is differentially regulated, our findings have suggested an important role for TNFα in the regulation of myocardin in VSMCs, and likely the pathogenesis of vascular diseases, such as atherosclerosis." (PMID 25384061, 2014). "Tumor necrosis factor-α (TNF-α) has been implicated in myocardial dysfunction resulting from acute coronary syndrome and high levels of C-reactive protein and IL-1 and IL-6 have been associated with subclinical atherosclerosis." (PMID 25374442, 2014). "The effects of TNF-α and inflammatory cytokines on induction of endothelial dysfunction are well described and are likely to represent key mediators of endothelial dysfunction and atherosclerosis." (PMID 24968272, 2014). "Additionally, beneficial effects of anti-TNF-α on adipokines, biomarkers of atherosclerosis, and MeS-related biomarkers were also found in AS." (PMID 24976690, 2014). "TNF-α may also be largely responsible for the endothelial dysfunction and accelerated atherosclerosis in these patients, making anti-TNF-α agents attractive therapeutic options for preventing CVD in this population." (PMID 24968272, 2014). "However, in the presence of atherosclerosis this balance disrupts leading towards an increase production of proinflammatory cytokines as interleukins 1, 2, and 6 (IL-1, 2, and 6) and tumor necrosis factor α (TNF-α), with further progression of the disease." (PMID 24049656, 2013). "The present findings extend these concepts to the gene network level, and delineates pathways related to NF-κB and TNF that are involved in inflammation and atherosclerosis, as well as focus genes related to ubiquitin, proteasome, histone, HNF4A, insulin and APP." (PMID 23874591, 2013). "IgG antibodies against herpesviruses, carotid intima-media thickness (cIMT), endothelial function through flow-mediated dilatation (FMD) of the brachial artery, and blood atherosclerosis biomarkers (hsCRP, TNF-α, IL-6, MCP-1, MDA, sCD14, sCD163, VCAM-1, ICAM-1, D-dimer, and PAI-1) were measured." (PMID 23717597, 2013). "In addition, elevated levels of TNF-α and IL-17 had a synergistic effect on promoting the development of atherosclerosis." (PMID 24312440, 2013). "The proinflammatory effects of Th22 in the development of atherosclerosis may be dependent on the synergistical effects of IL-22 and TNF-α, which are the main effective cytokines of Th22 cells." (PMID 24312440, 2013). "Importance of diet and role of TNF-α in atherosclerosis progression was further substantiated by a study in which the authors showed that ApoE−/−/TNF-α−/− double knockout mice had a 50% reduction in lesion size relative to ApoE−/− single knockouts when put on ‘Western-style’ high-fat diet." (PMID 23437105, 2013). "The reductions in TNFα and IFNγ may also have contributed to the reduced atherosclerosis IL1β and TNFα enhance macrophage-derived foam cell formation by inhibiting macrophage intracellular lipid catabolism." (PMID 23560095, 2013). "The effect of TNF-α on atherosclerosis further proved that Th22 cells may be one of the most important T cells involved in atherosclerosis." (PMID 24312440, 2013). "TNFα stimulates the expression of endothelial cell genes, including E-Selectin, which may promote atherosclerosis via leukocyte recruitment." (PMID 24349153, 2013). "This pro-inflammatory profile, a key factor in the development of atherosclerosis, is in agreement with other studies which have reported increased pro-inflammatory mediators, such as TNF-α and hsCRP, and reduced levels of anti-inflammatory and anti-atherogenic mediators, such as adiponectin." (PMID 23570342, 2013).
atherosclerosis (continued). "Together, our results indicate that agonism of 5-HT2A receptors is a novel approach to developing small-molecule based therapeutics for inflammatory diseases that involve TNF-α, especially for those of the vasculature and gut such as atherosclerosis and inflammatory bowel disease." (PMID 24098382, 2013). "In contrast, TNF production was reduced to a lesser extent than IL-10, unaffected or even slightly increased, when stimulated with LPS from P. gingivalis, one of infectious agent of atherosclerosis." (PMID 22556042, 2012). "In addition to being involved in the inflammatory process, most cytokines (TNF-α, IL-1, IL-6) play a role in the genesis and in the progression of atherosclerosis." (PMID 23036698, 2012). "It was known that inflammatory cytokines such as interleukin-1 and −4 (IL-1 and IL-4) and tumour necrosis factor-α (TNF-α) may coordinately induce gelatinase enzymes during progression of atherosclerosis." (PMID 22716287, 2012). "Moreover, it was shown that TNF level correlates strongly with the burden of atherosclerosis in healthy middle-aged men, severity of peripheral arterial disease, and also elevated risk of recurrent myocardial infarction." (PMID 22556042, 2012). "Our hypothesis about the potential role of TNF-α was based on a range of converging clinical and experimental data implicating this proinflammatory cytokine in atherosclerosis." (PMID 23316287, 2012). "TNF-α and IL-6 are critical cytokines that respond to the progression of atherosclerosis." (PMID 21226932, 2011). "More research is necessary to determine if raisin polyphenols decrease TNF-α expression, potentially inhibiting NFκB transcription of inflammatory cytokines and chemoattractant and adhesion molecules that play a key role in progression of atherosclerosis." (PMID 18416823, 2008). "Human and microbial HSP60activate vascular endothelial cells and macrophages directly through CD14 and p38 mitogen-activated protein kinasesignalling pathway in a similarmanner as bacterial lipopolysaccharide (LPS), leading to IL-6 and TNF-αsecretion and promotion of atherosclerosis." (PMID 18551190, 2008). "Inflammationplays a key role in mediating all stages of atherosclerosis which is considered a chronicinflammatory disease.Proinflammatory cytokines as TNF-alpha and IL-6 have both been shown to inducestructural as well as functional alterations in endothelial cells." (PMID 18437228, 2008). "Such evidence may suggest that drugs with an anti-TNFα action, such as B8, may be of benefit in atherosclerosis." (PMID 18671842, 2008). "Taken together these observations suggest that TNF-α may be functionally involved in early atherosclerosis development." (PMID 23675033, 2007). "TNF-α-inhibition could influence concomitant cardiovascular disease or even be used directly for treatment of atherosclerosis." (PMID 23675033, 2007). "To further evaluate this hypothesis we compared vascular TNF-α and TNF receptor expression in atherosclerosis-susceptible apoE-/-/LDL receptor-/- mice and control C57BL/6 mice." (PMID 23675033, 2007). "Several lines of evidence indicate that TNF-α, as well as other inflammatory cytokines, may also be involved in the development of atherosclerosis." (PMID 23675033, 2007). "An important question is whether TNF-α in itself plays a critical role in the development of atherosclerosis." (PMID 23675033, 2007). "This suggests that lipid-induced activation of TNF-α expression may play a role in endothelial activation and other inflammatory processes during early stages of atherosclerosis." (PMID 23675033, 2007). "Furthermore is the development of transplant atherosclerosis in rabbits inhibited by infusion of TNF-α blocking antibodies." (PMID 23675033, 2007). "This may be an explanation for why depletion of TNF receptors in this non-atherosclerosis prone mouse model doesn’t fit other observations that TNF-α would be a pro-atherogenic cytokine." (PMID 23675033, 2007).
atherosclerosis (continued). "TNF-α is thought to be responsible for endothelial dysfunction, thus could also play a role in atherosclerosis." (PMID 16674818, 2006). "Network pharmacology and molecular docking results revealed that several blood-brain barrier (BBB)-permeable active components of Lonicera caerulea, including Naringenin and Palmatine, may be associated with targets involved in the lipid and atherosclerosis pathway, such as HSP90AA1, SRC and TNF." (PMID 42196534, 2026). "Chronic HCV infection, for instance, is associated with an increased risk of atherosclerosis and coronary artery disease (CAD), likely mediated by persistent immune activation and elevated levels of proinflammatory cytokines like tumor necrosis factor-alpha (TNF-α) and interleukin-6 (IL-6)." (PMID 40787484, 2025). "TNF inhibitors, including infliximab, etanercept, adalimumab, certolizumab pegol, and golimumab, effectively reduce systemic inflammation, a key driver of atherosclerosis and CVD, and improve outcomes such as reduced risks of myocardial infarction and cerebrovascular events." (PMID 40376321, 2025). "The results showed that Jiawei Shoutai Pill could treat DOR through reactive oxygen species metabolism, oxidative stress, lipopolysaccharide metabolism and other related biological processes, as well as the phosphoinositide 3-kinase (PI3K)–AKT, TNF, lipid, and atherosclerosis signaling pathways." (PMID 40020109, 2025). "Pro-atherogenic T helper 1 (Th1) cells secrete interferon (IFN)-γ and tumor necrosis factor (TNF)-α, which promote the expression of adhesion molecules on endothelial cells, the activation of macrophages and hypertriglyceridemia, thereby aggravating atherosclerosis." (PMID 40603813, 2025). "Others also observed a positive correlation between TGF-β and TNF-α, which could be attributed to balanced expression of anti- or pro-inflammatory cytokines, characteristic of chronic inflammation in the arterial wall with atherosclerosis." (PMID 40868095, 2025). "Protocatechuic acid dose-dependently inhibited the inflammation response, as evidenced by a reduction in IL-1β, IL-6, and TNF-α at the mRNA and protein levels in MLCs stimulated or unstimulated with 50 pg/mL of LPS, a reachable level in patients or laboratory animals with atherosclerosis." (PMID 40292571, 2025). "Notably, the pathways that might be related to NSCLC included lipid and atherosclerosis, the TNF signaling pathway, the IL-17 signaling pathway, transcriptional misregulation in cancer, pathways in cancer, the PPAR signaling pathway, and others." (PMID 39440769, 2025). "This review explores the intricate interplay between inflammatory mediators—such as tumor necrosis factor-alpha (TNF-α), interleukin-6 (IL-6), and interleukin-17 (IL-17),—adipokine imbalances, and lipid metabolism abnormalities, all of which foster endothelial dysfunction and atherosclerosis." (PMID 40137170, 2025). "Therefore, TNF signaling pathway may be a promising treatment target for patients with gout complicated with atherosclerosis." (PMID 38368442, 2024). "In human umbilical vein endothelial cells, TNF-α binds to TNFR1 and stimulates the expression of vascular cell adhesion molecule-1, intercellular adhesion molecule-1, and E-selectin by causing downstream NF-κB activation, thereby increasing endothelial inflammation and atherosclerosis." (PMID 38612557, 2024). "Additionally, we found that the enriched KEGG terms were lipid and atherosclerosis, Toll-like receptor signaling pathway, TNF signaling pathway, leukocyte transendothelial migration, neurotrophin signaling pathway, apoptosis, and neutrophil extracellular trap formation." (PMID 38956669, 2024). "Unexpectedly, the absence of the TNFα p55 receptor in mice was found to be associated with increased atherosclerotic lesion development compared to wildtype mice, indicating the TNFα receptor is protective against atherosclerosis." (PMID 38256155, 2024).
atherosclerosis (continued). "Thus, TNF may be an important link connecting the pathophysiological mechanisms of gout and atherosclerosis." (PMID 39677038, 2024). "Additionally, bilirubin can inhibit inflammatory responses by suppressing the release of various inflammatory mediators (e.g., TNF-α, IL-6), thus reducing inflammation-induced damage to vascular endothelial cells and preventing atherosclerosis and other cardiovascular diseases." (PMID 39188917, 2024). "IL‐38 was shown to inhibit the maturation of DCs in atherosclerosis by blocking the NF‐κB pathway, thereby increasing the expression of the anti‐inflammatory cytokine IL‐10 and reducing the expression of the pro‐inflammatory cytokines IL‐23, TNF‐α, and IFN‐γ expression." (PMID 38334236, 2024). "Also, studies have found that miR‐155 could increase the expression of inflammatory factors such as IL‐6 and TNF‐α in endothelial cells, promoting atherosclerosis progression." (PMID 39495676, 2024). "Therefore, increased MMP-9 gene expression, serum MMP-9 and TNF-α concentration in CAD patients could have key roles in pathophysiological state of vascular injury, susceptibility to plaque formation and atherosclerosis." (PMID 38357561, 2023). "Leptin, adiponectin, interleukin-6, and tumor necrosis factor are only a few cytokines and bioactive mediators released by adipose tissue, an active endocrine and paracrine organ that may affect blood flow and encourage atherosclerosis." (PMID 37168312, 2023). "Furthermore, regulating Shank3 expression may reduce inflammation-related disorders, such as atherosclerosis, by inhibiting tumor necrosis factor-alpha-mediated inflammatory cascades." (PMID 37947623, 2023). "The involvement of CRP in atherosclerosis is highlighted because it is a fundamental aspect of chronic inflammation, is highly resistant to proteolysis, and is primarily synthesized in the liver in response to proinflammatory cytokines like IL-6, IL-1β, and tumor necrosis factor (TNF)." (PMID 37860004, 2023). "Pathway enrichment analysis suggested that BYDE might control the cardiac inflammation via targeting the tumor necrosis factor-alpha (TNF-α)/nuclear factor-κB (NF-κB) pathway while the selected targets were also implicated in IL-17 signaling pathway, lipid and atherosclerosis." (PMID 36713834, 2023). "Generally, TNF-α concentrations are found to be elevated in various cardiovascular conditions (e.g., advanced health failure, cardiomyopathy) and may also induce vascular inflammation, which may contribute to the pathogenesis of atherosclerosis." (PMID 35205271, 2022). "Additionally, in apolipoprotein E knockout mice, TNF-α suppression lowers atherosclerosis." (PMID 36422550, 2022). "Another component that modulates TNFα-induced remodeling is the erythropoietin-producing human hepatocellular receptor (EphA), which is a receptor tyrosine kinase that mediates cell-adhesion and leukocyte homing in atherosclerosis by promoting ICAM1 and VCAM1 expression on ECs." (PMID 35600479, 2022). "In apolipoprotein E-deficient mice model, CCL4 antibody treatment reduced circulating IL-6 and TNF-α whereby the authors concluded that CCL4 inhibition seems to be a promising tool within the box of anti-inflammatory therapeutics in patients diagnosed with atherosclerosis." (PMID 36290379, 2022).